TRIM3 (tripartite motif containing 3)
Diseases named in the same sentence as TRIM3 in open-access papers (continued):
Sharing a sentence is not in itself a finding about the gene and the disease.
colorectal cancer (6 papers, 2018 to 2025). A primary or metastatic malignant neoplasm that affects the colon or rectum. "One study found that overexpression of TRIM3 can inhibit metabolic pathways such as glycolysis and oxidative phosphorylation in colorectal cancer cells, causing the quelling of their growth and invasion." (PMID 38411731, 2024). "A particular study identified a significant downregulation of TRIM3 in colorectal cancer tissues, and the expression level of TRIM3 was closely associated with the clinical and pathological hallmarks of colorectal cancer." (PMID 38411731, 2024). "Abnormal expression of TRIM3 is closely linked to the occurrence and progression of various tumors, including glioma, liver cancer, and colorectal cancer." (PMID 38411731, 2024). "As a result, TRIM3 emerges as a promising new target for the treatment of colorectal cancer, given its potential to inhibit invasion and metastasis, induce apoptosis, and regulate essential signaling pathways involved in colorectal cancer progression." (PMID 38411731, 2024). "The LncRNA FAL1, emanating from CAFs, functions as a “molecular scaffold” for Beclin1 and TRIM3 within colorectal cancer cells, augmenting the ubiquitination and proteasomal degradation of Beclin1 by TRIM3 and consequently repressing autophagy." (PMID 39717771, 2024). "The overexpression of TRIM3 significantly curbs the proliferation and growth, while simultaneously resulting in apoptosis of colorectal cancer cells." (PMID 38411731, 2024). "TRIM3 demonstrates significant potential in inhibiting the invasion and metastasis of colorectal cancer cells." (PMID 38411731, 2024). "TRIM3 can also modulate the mitochondrial function of colorectal cancer cells, further contributing to the impediment of their growth and invasion." (PMID 38411731, 2024). "A study has revealed that overexpression of TRIM3 leads to a substantial diminution in the invasion and metastasis capabilities of colorectal cancer cells, along with a decreased migration ability." (PMID 38411731, 2024). "Research has demonstrated that TRIM3 acts as a hindrance to the NF-κB signaling pathway, creating a decreased proliferation and invasion of colorectal cancer cells." (PMID 38411731, 2024). "Recent studies showed that the expression level of TRIM3 in colorectal cancer is much less than that in normal colorectal tissue." (PMID 38411731, 2024). "Furthermore, TRIM3 induces apoptosis in colorectal cancer cells and regulates their metabolism, effectively impeding the occurrence and progression of colorectal cancer." (PMID 38411731, 2024). "Furthermore, the expression level of TRIM3 has a direct link with the prognosis of colorectal cancer, as sufferers with lesser TRIM3 expression tend to experience poorer outcomes." (PMID 38411731, 2024). "TRIM3 can regulate the metabolism of colorectal cancer cells." (PMID 38411731, 2024). "Consequently, TRIM3 also limits the proliferation and self-renewing capabilities of colorectal cancer stem cells, thus inhibiting the onset and development of colorectal cancer." (PMID 38411731, 2024). "Furthermore, TRIM3 exerts its inhibitory action by suppressing the expression of downstream target genes in the Wnt/β-catenin signaling pathway, such as c-Myc and CyclinD1, thus curtailing the proliferation and invasion of colorectal cancer cells." (PMID 38411731, 2024). "Research has shown that TRIM3 can hinder the energizing of the PI3K/Akt signaling, effectively restraining the proliferation and invasion of colorectal cancer cells." (PMID 38411731, 2024). "In addition, TRIM3 can also suppress the expression of downstream target genes in the PI3K/Akt signaling pathway, such as Bcl-2 and Mcl-1, thus promoting apoptosis in colorectal cancer cells." (PMID 38411731, 2024).
colorectal cancer (continued). "By hindering the nuclear transport and DNA-binding capacity of NF-κB, TRIM3 effectively deactivates this signaling pathway and downregulates the downstream target genes, such as IL-6 and TNF-α, thus curbing the inflammatory response and invasion abilities of colorectal cancer cells." (PMID 38411731, 2024).
liver cancer (6 papers, 2017 to 2024). An epithelial or non-epithelial malignant neoplasm that arises from the liver. "Conversely, when the expression of TRIM3 is reduced, the proportion of liver cancer cells in the S and G2/M phases increases." (PMID 38411731, 2024). "Emerging research has demonstrated that TRIM3 expression is diminished in liver cancer and exhibits pronounced anticancer effects." (PMID 38411731, 2024). "Overexpression of TRIM3 can curtail the proliferation capacity of liver cancer cells by regulating related signaling pathways, such as PI3K/Akt, MAPK, and Wnt/β-catenin, which affect the cell cycle and proliferation-related gene expression." (PMID 38411731, 2024). "Since this article only collected the TRIM3 expression and HCC patient information from online databases, the role of TRIM3 in liver cancer needs to be verified with more databases, cell lines, clinical samples, and experimental researches." (PMID 35004288, 2021). "Our study also showed that TRIM3 overexpression inhibited the migration and invasion of liver cancer cells." (PMID 28950898, 2017). "In summary, our results demonstrated that TRIM3 suppressed the tumorigenicity of liver cancer cells by inhibiting proliferation, colony formation, migration, and invasion and by inducing cell cycle arrest of tumor cells." (PMID 28950898, 2017). "TRIM3 plays a tumor-suppressing role in the regulation of liver cancer development by reducing cell proliferation through cell cycle arrest at the G0/G1 phase." (PMID 28950898, 2017). "To elucidate the potential role of TRIM3 in the development of liver cancer, we investigated the functions of TRIM3 in liver cancer cell lines." (PMID 28950898, 2017). "We estimated the protein expression levels of TRIM3 in five liver cancer cell lines by Western blotting." (PMID 28950898, 2017). "The protein levels of TRIM3 in five liver cancer cell lines (SK-Hep1, Hep3B, Huh7, HepG2, Bel-7402) and one normal liver cell line (L02) were detected with Western blotting." (PMID 28950898, 2017). "Compared with the normal liver cell line L02, five liver cancer cell lines (SK-Hep1, Hep3B, Huh7, HepG2, and Bel-7402), especially Bel-7402 and HepG2, had lower levels of TRIM3." (PMID 28950898, 2017). "In the present study, we found that TRIM3 expression was lower in liver cancer cells than in normal liver cells." (PMID 28950898, 2017). "TRIM3 mitigates tumor growth in liver cancer by making cell cycle arrest in tumor cells." (PMID 38411731, 2024). "In addition, TRIM3 overexpression reduces the number of tumor stem cells and hinders tumor angiogenesis, effectively restraining tumor growth and metastasis in liver cancer." (PMID 38411731, 2024). "Besides liver cancer cells with low TRIM3 expression, those with high TRIM3 expression exhibit a noteworthy boost in the ratio of cells in the Go/G1 phase and a significant decrease in the percentage of cells in the G2/M phase." (PMID 38411731, 2024). "Furthermore, TRIM3 is downregulated in various types of cancer, including liver cancer, esophageal squamous cell carcinoma, and colon cancer, and inhibits cell proliferation, invasion, and metastasis." (PMID 34508066, 2021). "It was validated that overexpression of TRIM3 could induce G0/G1 phase arrest, reducing cell proliferation in liver cancer." (PMID 35004288, 2021). "Taken together, although the precise molecular mechanism by which TRIM3 regulates liver cancer progression remains unknown, our results suggest that TRIM3 may serve as a tumor suppressor in liver cancer." (PMID 28950898, 2017). "This study aimed to investigate the function of TRIM3 in liver cancer cells." (PMID 28950898, 2017). "Hence, TRIM3 has a certain inhibitory job in the occurrence and development of liver cancer." (PMID 38411731, 2024). "However, whether TRIM3 acts on cell cycle-related proteins in liver cancer needs to be determined in future studies." (PMID 28950898, 2017).
liver cancer (continued). "Furthermore, we performed in vivo metastasis assay in nude mice to investigate whether TRIM3 overexpression could alter the in vivo metastatic ability of liver cancer cells." (PMID 28950898, 2017). "However, the precise molecular mechanism by which TRIM3 suppresses liver cancer cell metastasis remains uncertain, whether TRIM3 acts on cell mobility-related proteins in liver cancer needs to be determined in future studies." (PMID 28950898, 2017). "We studied the effects of TRIM3 on migration and invasion of liver cancer cells using transwell assays with or without Matrigel, respectively." (PMID 28950898, 2017). "Cell apoptosis analyses showed that TRIM3 overexpression did not significantly affect apoptosis, suggesting that TRIM3 may not play a role in the apoptosis of liver cancer cells." (PMID 28950898, 2017). "Therefore, exploring TRIM3 as a potential therapeutic target could pave the way for novel strategies to combat liver cancer and improve patient outcomes." (PMID 38411731, 2024).
brain tumor (4 papers, 2009 to 2021). "Human Tripartite motif protein 3 (TRIM3) encodes a structural homolog of Drosophila brain tumor (brat) implicated in progenitor cell proliferation control and cancer stem cell suppression." (PMID 19250537, 2009). "TRIM3 is a candidate brain tumor suppressor gene, which suppresses brain tumorigenesis via attenuating Notch signaling and suppressing c-MYC expression." (PMID 34508066, 2021). "We opted for this unorthodox bottom-up strategy as a result of significant structural homologies between TRIM3 and the Drosophila brain tumor suppressor Brat, as well as owing to the fact that TRIM3 is located on chromosome segment 11p15.5." (PMID 19250537, 2009). "Loss of heterozygosity of chromosome segment 11p15.5 in malignant gliomas suggests TRIM3 as a candidate brain tumor suppressor gene." (PMID 19250537, 2009). "Further investigation will be needed to elucidate the biological function of TRIM3 and its precise role in brain tumor suppression." (PMID 19250537, 2009). "Among those genes are ASCL2 and ASCL3, mammalian homologues of Drosophila achaete-scute complex, as well as TRIM3, a homologue of Drosophila brain tumor involved in progenitor cell proliferation control and cancer stem cell suppression, and a cluster of more distantly related TRIM genes." (PMID 19250537, 2009). "Together, these data suggest TRIM3 as a 11p15.5 candidate brain tumor suppressor gene." (PMID 19250537, 2009). "It will be interesting to see whether TRIM3, similar to its Drosophila homologue Brain tumor, is involved in the regulation of progenitor cell proliferation control and brain tumor suppression." (PMID 19250537, 2009).
colon cancer (4 papers, 2020 to 2024). "Five TRIM expression was significantly upregulated (TRIM14, TRIM15, TRIM24, TRIM29, and TRIM31), and the other five TRIM genes showed decreased expression (TRIM1, TRIM3, TRIM9, TRIM22, and TRIM73) in both colon cancer (COAD) and rectal cancer (READ)." (PMID 38769340, 2024).
hepatocellular carcinoma (3 papers, 2017 to 2023). A malignant tumor that arises from hepatocytes. "In our previous research, we found that TRIM3 expression was markedly reduced in human primary hepatocellular carcinoma (HCC) tissues and that low TRIM3 expression was associated with short survival of HCC patients." (PMID 28950898, 2017). "It has been reported that the mRNA and protein levels of TRIM3 are downregulated in hepatocellular carcinoma (HCC) and are correlated with an unfavorable prognosis in patients with HCC, suggesting that TRIM3 could be a prognostic marker and novel therapeutic target for HCC." (PMID 30031392, 2018).
Parkinson disease (3 papers, 2020 to 2023). A progressive degenerative disorder of the central nervous system characterized by loss of dopamine producing neurons in the substantia nigra and the presence of Lewy bodies in the substantia nigra and locus coeruleus. "Another study has also supported the viewpoint that TRIM3 contributes to the early diagnosis and treatment of Parkinson’s disease." (PMID 35066729, 2023). "Work with in vivo and in vitro Parkinson’s disease (PD) models, showed that TRIM3 is involved in the reduction of an apoptotic phenotype in PD cells through the PI3K/Akt pathway." (PMID 36139694, 2022). "This article aims to study tripartite motif-containing protein 3 (TRIM3) effects on Parkinson's disease (PD)." (PMID 33253119, 2020).
breast tumors (2 papers, 2022). "Our data showed that TRIM3 depletion by lentivirus-based shRNA slowed breast tumor growth." (PMID 35392925, 2022).
Ewing sarcoma (2 papers, 2021 to 2023). A small round cell tumor that lacks morphologic, immunohistochemical, and electron microscopic evidence of neuroectodermal differentiation. "Furthermore, a recent study suggested that TRIM3 (Tripartite Motif Containing 3 inhibits autophagy in Ewing Sarcoma cells." (PMID 33652741, 2021). "The enhanced expression of TRIM3 markedly and continually hindered autophagy in Ewing sarcoma (ES) cells." (PMID 35066729, 2023).
lung carcinoma (2 papers, 2024 to 2026). "WB and qPCR analyses confirmed that TRIM3 expression was lower in lung cancer cells than in normal BEAS-2B bronchial epithelial cells." (PMID 41545343, 2026). "In subcutaneous tumor models of diverse tumors, unlike the responses to PD-1, PD-L1 and CTLA-4 inhibitors or other cytokines, TRIM3 mRNA expression decreased specifically upon IFN-β stimulation in the LLC lung cancer model." (PMID 41545343, 2026). "TRIM3 can diminish the activation of NF-κB, thereby suppressing the proliferation and invasion of lung cancer cells." (PMID 38411731, 2024). "Further experiments evidenced TRIM3’s ability to inhibit lung cancer cell proliferation and invasion and induce apoptosis." (PMID 38411731, 2024). "A study demonstrated significantly lower expression levels of TRIM3 in lung cancer tissue compared to normal lung tissue, with its expression level closely correlating with the clinical and pathological characteristics of lung cancer." (PMID 38411731, 2024). "Recent investigations have highlighted the crucial role of TRIM3 in suppressing lung cancer." (PMID 38411731, 2024). "Additionally, TRIM3 can also regulate the metabolism of lung cancer cells, curtailing metabolic pathways such as glycolysis and oxidative phosphorylation, thus hindering the growth and invasion of lung cancer cells." (PMID 38411731, 2024).
rheumatoid arthritis (2 papers, 2023). A chronic, systemic autoimmune disorder characterized by inflammation in the synovial membranes and articular surfaces. "TRIM3 overexpression has an inhibitory effect on the proliferation and cytokine secretion of fibroblast-like synoviocytes in rheumatoid arthritis and can protect against LPS-induced acute kidney injury by inhibiting the IRF3 pathway and NLRP3 inflammasome activation." (PMID 37520369, 2023).
viral infection (2 papers, 2010 to 2023). "In peripheral blood leukocytes, TRIM3 is mainly expressed in macrophages and can be up-regulated by viral infection." (PMID 21176133, 2010). "Tripartite motif-containing 3 (TRIM3), as a member of the TRIM protein family, may contribute to the regulation of the immune and inflammatory responses after viral infection." (PMID 37520369, 2023).
lung adenocarcinoma (1 paper, 2026). A carcinoma that arises from the lung and is characterized by the presence of malignant glandular epithelial cells. "The expression of TRIM3 mRNA was also significantly downregulated in most cancer types, including lung adenocarcinoma (LUAD) and squamous cell carcinoma (LUSC)." (PMID 41545343, 2026).
oligodendroglioma (1 paper, 2017). A well-differentiated (WHO grade II), diffusely infiltrating neuroglial tumor, typically located in the cerebral hemispheres. "Additionally, reducing TRIM3 expression promoted tumor development and accelerated the progression of oligodendroglioma in a mouse model." (PMID 28950898, 2017).
triple-negative breast carcinoma (1 paper, 2022). An invasive breast carcinoma which is negative for expression of estrogen receptor (ER), progesterone receptor (PR), and human epidermal growth factor receptor 2 (HER2). "However, in triple-negative breast cancer, the expression of TRIM3 is opposite." (PMID 35392925, 2022).